CDKN2A (cyclin dependent kinase inhibitor 2A)
Diseases named in the same sentence as CDKN2A in open-access papers (continued):
Sharing a sentence is not in itself a finding about the gene and the disease.
mesothelioma (continued). "A recent study indicated that Nf2; Cdkn2a-deficient mouse mesothelioma cells showed less malignant phenotypes with PAK2 loss, suggesting that anti-PAK drugs may be promising for mesothelioma treatment." (PMID 37180489, 2023). "Similarly, cuproptosis-associated genes including LIAS, LIPT1, PDHB, GLS, and CDKN2A had significant overall survival in Mesothelioma (MESO) (p < 0.05)." (PMID 36105090, 2022). "As the most frequent mutations/deletions, the collaborative inactivation of BAP1, NF2, and CDKN2A could result in rapid and aggressive mesothelioma, while homozygous mutation rarely results in carcinogenesis." (PMID 34299035, 2021). "In addition, research on mesothelioma genome supports the role of inactivated tumor suppressor genes encoded by cyclin-dependent kinase inhibitor 2A (CDKN2A), BRCA1 associated protein 1 (BAP1) and neurofibromin 2 (NF2)." (PMID 32050546, 2020). "The CDKN2A gene, located on chromosome 9p21, is the most frequently inactivated tumor suppressor gene in mesothelioma, with homozygous deletions occurring in 50–100% of cases." (PMID 40362535, 2025). "CDKN2A homozygous deletion has been established as a highly accurate biomarker for differentiating mesothelioma from benign mesothelial proliferations." (PMID 40566743, 2025). "Even when nuclear atypia and negative results for immunohistochemical tests for the three mesothelioma markers suggest carcinoma, mesothelioma should still be considered and p16/CDKN2A co-deletion should be evaluated." (PMID 40034201, 2025). "Although the resected tumor was not positive for any of the three histopathological markers of mesothelioma, CDKN2A co-deletion revealed by fluorescence in situ hybridization led to a diagnosis of malignant mesothelioma." (PMID 40034201, 2025). "Homozygous deletion of BAP1 and cyclin-dependent kinase inhibitor 2A (CDKN2A/p16) by fluorescence in situ hybridisation (FISH) is highly specific for mesothelioma." (PMID 41147025, 2025). "In this study, we employed a quantitative proteomic mass spectrometry approach to assess alterations in protein expression following EZH2 inhibition in BAP1- and CDKN2A-proficient mesothelioma cells cultured as spheroids." (PMID 41226368, 2025). "The immune cell composition in BNC closely resembles that in human mesothelioma with BAP1, NF2, and CDKN2A loss—M2 macrophages, T cells, and B cells make up a significant proportion of the leukocyte population." (PMID 38879686, 2024). "Several studies have investigated MTAP IHC as a marker of CDKN2A status in various tumor types such as diffuse glioma, pleomorphic xantroastrocytoma, and mesothelioma." (PMID 39409918, 2024). "Given the close proximity of the CDKN2A and MTAP genes, loss of MTAP immunoreactivity has been suggested as a surrogate for CDKN2A HD and has been demonstrated in mesothelioma." (PMID 37504251, 2023). "In line with our findings, previous publications reported genomic CDKN2A alterations in 42% of all mesothelioma patients." (PMID 37345150, 2023). "In situ mesothelioma needs to be diagnosed by immunohistochemical detection of BAP1 and/or MTAP loss, and/or by fluorescence in situ hybridization detection of CDKN2A homozygous deletion, and fully discussed with thoracic surgeons and radiologists in MDT." (PMID 37461124, 2023). "Conditional knockout mice targeting Nf2, Bap1, and/or Cdkn2a in cells of the mesothelium exhibited an increased incidence of mesothelioma, and noticeably, the triple-knockout mice showed highly invasive tumors with the shortest survival times." (PMID 37180489, 2023).
mesothelioma (continued). "Both the mesothelioma in situ and invasive lesion showed immunohistochemical loss of methylthioadenosine phosphorylase (MTAP) and homozygous deletion of cyclin dependent kinase inhibitor 2A (CDKN2A) on fluorescence in situ hybridization." (PMID 38017544, 2023). "The authors of this study, based on the presence, absence or co-occurrence of CDKN2A/B and BAP1 mutations, identified four mesothelioma subgroups with different prognostic impact." (PMID 37046732, 2023). "CDKN2A inactivation is present in approximately 50% of mesotheliomas and can be reliably detected by fluorescent in situ hybridization (FISH), or by immunostain for MTAP, a gene that is most frequently co-deleted with the nearby CDKN2A gene." (PMID 37880686, 2023). "One of the significant aspects noted herein is that both the MIS and invasive mesothelioma exhibited loss of methylthioadenosine phosphorylase (MTAP) and homozygous deletion of cyclin-dependent kinase inhibitor 2A (CDKN2A)." (PMID 38017544, 2023). "In one mesothelioma with heterozygous CDKN2A-MTAP deletion, positive MTAP expression was seen in 60% of the tumor cells, whereas p16 was completely negative." (PMID 37894345, 2023). "Similar to studies in mesotheliomas, we also identified one lymphoepithelial carcinoma with the preserved expression of mTAP despite the homozygous deletion of CDKN2A." (PMID 35565429, 2022). "Specifically, homozygous deletion of CDKN2A has been found in 48 to 78% of epithelioid and 67 to 100% of sarcomatoid mesotheliomas." (PMID 35565429, 2022). "In a study of 40 mesotheliomas, homozygous deletion of CDKN2A occurred together with homozygous (n = 5) or heterozygous (n = 5) deletion of MTAP or normal MTAP (n = 3)." (PMID 35565429, 2022). "Earlier studies showed a homozygous deletion of CDKN2A in 74% of mesothelioma samples and co-deletion of MTAP in 91% of these cases." (PMID 36138075, 2022). "Given that CDKN2A is deleted in approximately 45% of mesothelioma cases, palbociclib, a CDK4/6 kinase inhibitor, has been tested for its ability to induce cell-cycle arrest and senescence in mesothelioma." (PMID 34226685, 2021). "The detection of homozygous CDKN2A deletion by FISH would have been helpful in confirming a diagnosis of mesothelioma over reactive mesothelial cells in 12 of 13 samples with positive or suspicious cytology." (PMID 35004697, 2021). "Another tested drug in our screen, Palbociclib, PD0332991, a CDK4/CDK6 inhibitor, that is supposed to target the most frequent deletion in mesothelioma, CDKN2A, showed only minor effects in our cell lines." (PMID 34580349, 2021). "CDKN2A silencing in combination with EPZ-6438 treatment induced apoptotic death in mesothelioma spheroids." (PMID 34277422, 2021). "Deletion of the CDKN2A region is extensive in many malignancies and a full locus map revealed large deletions to also be present in mesothelioma." (PMID 34580349, 2021). "FISH detection of CDKN2A (p16) homozygous deletion is an effective way to evaluate sarcomatoid component in mesothelioma." (PMID 34331411, 2021). "This recapitulates the histological features and gene profile observed in human patients carrying combined BAP1, NF2 and CDKN2A alterations, indicating that the combined deletion of these tumor-suppressor genes creates a mesothelioma-specific microenvironment." (PMID 34830817, 2021). "Fiber-induced CDKN2A disruption has also been observed in a study in which mesothelioma was induced in mice by instillation of either asbestos fibers or long-fiber carbon nanotube (CNTs) into the pleural cavities." (PMID 31138176, 2019).
mesothelioma (continued). "Through whole exome sequencing of tumour cell lines developed from mesotheliomas from three murine strains, we have shown that the Cdkn2a gene is consistently lost in the asbestos-induced wild-type murine model of MM." (PMID 28577549, 2017). "A common chromosomal deletion was detected at 5q32, containing the Cdkn2a gene, and a homozygous deletion was observed in the majority of cases from epithelioid to sarcomatoid and biphasic mesotheliomas." (PMID 27129173, 2016). "Cdkn2a also represents a tumor suppressor gene that has previously been reported to represent a target for biological studies on mesothelioma." (PMID 27129173, 2016). "Another work studied CNVs in 22 mesothelioma patients and identified lost copies of CDKN2A and CDKN2B tumor suppressor genes." (PMID 26185765, 2015). "It was noted earlier that p16 expression levels were higher in TAg tumours and TAg mesothelial cells compared to wild type mesotheliomas, due to deletion of the cdkN2A locus in the latter samples." (PMID 26680231, 2015). "Deletions of chromosome arms 3p, 9p and 22q, which include the tumor suppressor genes BAP1, CDKN2A, and NF2, respectively, have all been linked to mesothelioma." (PMID 25952750, 2015). "A potential candidate for this approach would be the Cdkn2a gene (encoding P16Ink4a and P19ARF) that has recently been shown to genetically interact with Nf2 mutations in the development of mesothelioma." (PMID 26258444, 2015). "In the mesothelioma samples, whose signal intensity at the Cdkn2a/2b locus was largely lower than −1, they found homozygous deletion of the gene." (PMID 25410479, 2014). "Mesothelioma is characterized by the inactivation of tumor suppressor genes, with frequent mutations in neurofibromin 2 (NF2), BRCA1-associated protein 1 (BAP1), and cyclin-dependent kinase inhibitor 2A (CDKN2A)." (PMID 40362535, 2025). "Mesotheliomas exhibit extensive aneuploidy and are driven by copy number alterations affecting a restricted number of tumour suppressors, which include loss of 3p21 (harbouring BAP1) and 9p21 (CDKN2A)." (PMID 39168966, 2024). "Three of the most frequent clonal genetic alterations that occur in human mesothelioma cells are somatic mutations and deletions of the tumor suppressor genes BAP1, CDKN2A/B, and NF2, and germline mutation of BAP1 is a well-established genetic risk factor for mesothelioma." (PMID 38784478, 2024). "Furthermore, cases of mesothelioma, even those of an in situ lesion, with MTAP loss and/or CDKN2A deletion should be carefully followed up or subjected to early treatment." (PMID 38017544, 2023). "A pilot study of chemotherapy treatment using previously published doses, revealed CNP mice to be extremely sensitive to chemotherapy-induced toxicity, requiring reduction of both drugs to half the concentrations used in mesothelioma mouse model driven by triple deletion of Bap1, Cdkn2a and Nf2." (PMID 37441092, 2023).
mesothelioma (continued). "The scarcity of actionable mutations in mesothelioma limits the application of targeted drug treatments, and therefore, many trials have focussed on pathways affected by genetic alterations affecting BAP1, CDKN2A and NF2." (PMID 38015374, 2023). "The IFNB1 gene is co-deleted in 70% of mesothelioma with CDKN2A deletion." (PMID 37296931, 2023). "Almost all of our mesothelioma cases exhibited a loss of MTAP and CDKN2A." (PMID 33304846, 2020). "Additionally, abnormal copy number of CDKN2A in MPM tumor cells associated with high pulmonary asbestos fiber count, again suggesting a biological difference between mesotheliomas depending on the degree of asbestos exposure." (PMID 31138176, 2019). "Clinically relevant markers of mesothelioma, transcriptional and metabolic profiles, as well as status of the tumor suppressor genes CDKN2A and NF2, the ‘gatekeeper' in MM development, were examined in the primary cell lines and compared with those of two widely used commercial cell lines." (PMID 26891694, 2016). "Since the p16INK4a/p14ARF proteins encoded by the CDKN2A locus are essential for normal cell cycle control, FISH analysis of this locus can be useful for the diagnosis of early-stage mesotheliomas of epithelial type." (PMID 25952750, 2015). "Mutations in known mesothelioma-related genes NF2, CDKN2A, LATS2, amongst others, were identified." (PMID 25798586, 2015). "CDKN2A (cyclin-dependent kinase inhibitor 2A) encoding the p16ink4a that inhibits pRb phosphorylation is almost always deleted in mesothelioma, resulting in normal but non-functional pRB expression, was not differentially expressed." (PMID 19662092, 2009). "In our case study, the mesothelioma did not have either the BAP1 or CDKN2A mutation." (PMID 35664766, 2022). "However, one study of 17 mesotheliomas identified a single case that showed loss of mTAP expression without an identifiable homozygous CDKN2A deletion." (PMID 35565429, 2022). "Molecular genetic analysis of mesothelioma revealed frequent copy number loss and recurrent somatic mutations in TSGs such as BRCA1-associated protein 1 (BAP1, 60% of the cases), neurofibromin 2 (NF2, 75% of the cases), and cyclin-dependent kinase inhibitor 2A (CDKN2A, 60% of the cases)." (PMID 34299035, 2021). "Moreover, the importance of a homozygous deletion of CDKN2A/2B was found in rat mesothelioma with the suggestion that this deletion seems to be fundamental for the development of mesothelioma, since these genes are also known to be homozygously deleted in human mesothelioma." (PMID 22007251, 2011). "Moreover cytogenetic studies have shown that mesotheliomas have highly complex and variable chromosomal aberrations, and only few common important features have been identified, as the deletion of 9p21 including the CDKN2A gene." (PMID 19662092, 2009).
mesothelioma (continued). "Recent studies have indicated that the lack of BAP1 and MTAP expression, along with the homozygous deletion of CDKN2A identified through FISH, can effectively differentiate mesothelioma from benign proliferations." (PMID 40432917, 2025). "Genetic alterations in mesothelioma commonly include BAP1, CDKN2A, and moesin-ezrin-radixin-like tumor suppressors, which play important roles in mesothelioma development." (PMID 39006698, 2024). "Due to its proximity to CDKN2A, homozygous deletion of MTAP occurs frequently in various tumors, including mesotheliomas." (PMID 37894345, 2023). "Often expressed in mesothelioma, CDKN2A regulates the cell cycle by inhibiting the tumor suppressor p16ink4A, an endogenous suppressor of cyclin-dependent kinase (CDK) 4 and CDK6." (PMID 37445594, 2023). "Whereas the higher rate of overexpression in two target genes (CDKN2A and RET) represent high OS and lower expression show the small OS time in mesothelioma." (PMID 36139498, 2022). "In mesotheliomas, MTAP has been shown to be frequently co-deleted with CDKN2A; both genes are located close to each other on chromosome 9p21." (PMID 35565429, 2022). "In addition, although BAP1 loss and CDKN2A/p16 homozygous deletion have emerged as reliable markers for the differential diagnosis of benign mesothelial proliferation versus mesothelioma, they were revealed not to be appropriate for distinguishing mesothelioma from other malignant tumors." (PMID 36552912, 2022). "Significantly, we discovered that epigenetic silencing of Cdkn2a (Ink4a/Arf) and deletion of p19Arf observed in LNT-induced tumors recapitulates common features of human asbestos-induced mesothelioma." (PMID 29112861, 2017). "The most commonly inactivated tumor suppressor genes in mesothelioma are NF2, BAP1, and CDKN2A." (PMID 40362535, 2025). "CDKN2A homozygous deletion (HD), detected by fluorescent in situ hybridization (FISH), is a reportedly useful biomarker to distinguish between benign mesothelial proliferations and mesothelioma, especially in the pleura." (PMID 40566743, 2025). "While these synthetic agents effectively delayed tumor onset in asbestos-exposed Nf2+/−;Cdkn2a+/− mice, mesothelioma was not prevented." (PMID 38784478, 2024). "Although not investigated, this may correspond to differences in tumour growth seen in mesothelioma mouse models where co-alterations of BAP1, NF2 and CDKN2A/B led to a faster tumour growth compared to tumours with alterations in only one or two genes." (PMID 36138075, 2022). "Interestingly, in 55 to 91% of mesotheliomas, CDKN2A deletions have been described in tandem with deletions of MTAP, a gene that is located close to CDKN2A on chromosome 9p21." (PMID 35565429, 2022). "This HAND2-expressing group of mesothelioma tumors did not cluster notably with tumors featuring differential expression of the common mesothelioma-associated tumor suppressor genes BAP1 and CDKN2A." (PMID 35354817, 2022). "Mesothelioma (MESO) is an exception: significantly more CDKN2A deletion was detected in non-metastatic MESO than net distant metastatic MESO (p=0.045)." (PMID 35004325, 2021). "This gave rise to a multi-arm stratified therapy based clinical trial for patients with CDKN2A negative relapsed mesothelioma." (PMID 32526924, 2020). "Although disruption of the CDKN2A (INK4A/ARF) locus has been reported in end-stage disease, information is lacking on the status of this key tumor suppressor gene in pleural lesions preceding mesothelioma." (PMID 29112861, 2017). "Similarly, a subset of mesotheliomas harbors homozygous deletion of CDKN2A, which has not been identified in reactive mesothelial proliferation." (PMID 35565429, 2022). "Similarly, high mRNA levels of CDKN2A correlated with overall survival (OS) in ACC (Adrenocortical carcinoma), KIRC, LIHC, MESO (Mesothelioma), PCPG (Pheochromocytoma and Paraganglioma) and UCEC tumors, with p-values of 0.010, 0.029, 0.001, 0.001, 0.005 and 0.001, respectively." (PMID 35004697, 2021).